IL1B (interleukin 1 beta)
Diseases named in the same sentence as IL1B in open-access papers (continued):
Sharing a sentence is not in itself a finding about the gene and the disease.
influenza (194 papers, 2008 to 2026). An acute viral infection of the respiratory tract, occurring in isolated cases, in epidemics, or in pandemics; it is caused by serologically different strains of viruses (influenzaviruses) designated A, B, and C, has a 3-day incubation period, and usually lasts for 3 to 10 days. "IL-6 is involved in the development of cytokine release syndrome, with elevated levels of IL-6 and IL-1β being closely associated with poor prognoses in influenza patients and animal models." (PMID 40338080, 2025). "QIV also showed higher cytokine levels associated with influenza-induced inflammation, such as IL-1β, TNFα, IL-2, and IL-6, similar to the PBS group, which did not control viral replication well." (PMID 39975920, 2025). "In a previous study, we linked moDC (also referred to as inflammatory DCs) to IL-1β production in pigs, while moDCs have also been implicated in pathogenic anti-influenza immune responses." (PMID 40484956, 2025). "Apart from analyzing antiviral activity, the authors also studied the levels of NF-κB and proinflammatory cytokines, such as TNF-α, IL-1β, and IL-6, generally associated with influenza infection, which were reduced by the treatment with the HA2 dendrimer." (PMID 38140131, 2023). "Severity of influenza, another disease with cytokine storm-based pathogenesis has been associated also with IL1B gene polymorphism." (PMID 35059462, 2022). "Mucosal delivery of recombinant adenoviral vectors (rAd) encoding IL-1β enhanced influenza HA-specific antibody responses." (PMID 33430259, 2021). "Exposure to PB1-F2 peptide from pathogenic influenza increased IL-1β secretion compared to PB1-F2 from seasonal influenza." (PMID 33499234, 2021). "Despite their reported antiviral effect, IL-1β and IL-6 have been implicated in pulmonary inflammation during influenza infection." (PMID 34912341, 2021). "Succinate also provides an avenue for increased mtROS response, which in itself is pathogenic during influenza by upregulating pro-inflammatory IL-1β, in turn downregulating the expression of the antiviral IFN-β." (PMID 32008371, 2020). "Systemic delivery of bNAbs to treat influenza infections caused the proinflammatory cytokines IL-1α and IL-1β levels to rise even higher than those seen in untreated infected animals." (PMID 32847855, 2020). "In pharmacologic studies in which IL-1β or IL-1R was antagonized, influenza associated lung injury was reduced." (PMID 32655582, 2020). "IL-1β secretion, which contributes to inflammasome activation and has been implicated in influenza pathology, was increased in infected pregnant mice." (PMID 32922392, 2020). "In our study, genotype AA of IL-1β; rs16944 was shown to have significant association with influenza severe infection." (PMID 31196204, 2019). "Maternal immune activation (e.g., via an infectious exposure such as influenza) has been reported to be associated with risk of SZ and autism, and blood levels of cytokines (e.g., IL1B, IL2RA, IL-6, and TNF) are elevated in SZ patients (see reviews)." (PMID 30115913, 2018). "Similar MBL deficiencies lead to increased infection by influenza and exaggerated macrophage activation and increases in inflammatory cytokines, such as IL-1β and TNFα." (PMID 28619036, 2017). "Taken together our data showed that in addition to contributing to lung dysfunction, IL-1β played a key role in driving neutrophilic inflammation during influenza-induced exacerbations, an effect that was tightly linked to IL-17A expression." (PMID 24918427, 2014). "Acute influenza infection with pulmonary complications was associated with high plasma concentrations of IL-1β, IL-6, IL-12, and IFN-γ." (PMID 24696530, 2014). "The rs1143627 SNP located on 31 base pairs upstream from the transcription start site of IL1B gene was evaluated for the association with increased risk of influenza susceptibility." (PMID 23927441, 2013).
influenza (continued). "Pro-inflammatory cytokines, including TNF-α, interleukin (IL)-1β, and IL-6 have been implicated in the loss of appetite and weight in influenza infection, chronic inflammatory disorders and cancer." (PMID 22536437, 2012). "Prevention of platelet aggregation using other compounds has also been shown to improve survival in mouse models of severe influenza and is associated with reduced inflammation, reduction in proinflammatory cytokine levels (IL-1β, IL-6, TNF-α, and MIP-2) and reduced platelet activation." (PMID 33499234, 2021). "Consistent with this, intranasal delivery of IL‐1β or mucosal delivery of IL‐1β‐encoding adenoviral vectors along with influenza vaccine boosts immune responses against influenza infections, demonstrating that its immune‐stimulatory effect is physiologically important." (PMID 32428336, 2020). "Patients with influenza-associated acute encephalopathy/encephalitis exhibited neurological symptoms like seizure, altered arousal, and abnormal behaviors, which were associated with increased concentrations of IL-1β, IL-6, and TNF-α in serum and CSF." (PMID 32850927, 2020). "Also, in comparison with ILI group, the genotypes AA, GA, GG of IL-1β; rs16944 in influenza B group were statistically significant, which were associated with the risk of influenza infection (p = 0.014)." (PMID 31196204, 2019). "In this regard, some studies suggested that SNPs in the IL-10 and IL-1β genes might be associated with the severe outcome in influenza outbreak." (PMID 31196204, 2019). "The significance of this and the role of the IL-1β associated inflammasome in the response to H5 influenza in the chicken are currently unknown." (PMID 27631618, 2016). "Interestingly, IL-1β has been implicated in the control of efficient IgM responses to influenza infection and gut IgA production." (PMID 27898728, 2016). "Indeed, this allele is also associated with other diseases that involve IL-1β-dependent inflammation or cell death, such as influenza, keratoconus, and coronary artery disease." (PMID 25329476, 2014). "The suite of cytokines and chemokines assessed here, namely, TNF-α, IL-6, CCL2, CCL3, CXCL2 and IL-1β, are known to promote the inflammation caused by influenza at early stages of the infection phase, i.e. during the cytokine storm, and have been shown to underpin the pathology and morbidity." (PMID 23577160, 2013). "Thus, rs1143627 SNP in IL1B gene showed significant association with increased susceptibility to influenza." (PMID 23927441, 2013). "Furthermore, genetic variants in IL1B contribute to influenza susceptibility in humans." (PMID 34434199, 2021). "Additionally, in the present study, we found that through comparison of SNPs frequency of flu A-, flu B- and flu A + B- infected patients with ILI group, the IL-1β and IL-17 genotypes (GG, GA and AA) might be associated with the severe influenza infection." (PMID 31196204, 2019). "The elevated levels of proinflammatory cytokines (TNFα, IL-1β and IL-10) during influenza infection have also been primarily associated with increased lung pathology and worse outcomes, but it is uncertain whether some of these cytokines could also be protective during seasonal influenza infection." (PMID 29545521, 2018). "This suggests that the GC response to influenza infection promotes B cells expression of IL-1β required for the crosstalk between B and T cells post infection." (PMID 40825032, 2025). "Increased level of IL-6, IL-1β, TNFα, and IFN-β in response to influenza can damage the placenta and cause intrauterine fetal growth impairments." (PMID 41567998, 2025). "Using B cell specific ablation of IL-1β production and T cell specific ablation of IL-1R1 signaling post influenza infection, we show that B cell-derived IL-1β is essential for the establishment of TFH cells and therefore GCs." (PMID 40825032, 2025).
influenza (continued). "To evaluate the involvement of mast cells in our models, we assessed lung mast cell numbers following treatment with IL-1β/IL-23 or LPS and used influenza infection as a positive control for mast cell induction." (PMID 40674143, 2025). "We found that influenza infection significantly increased the numbers and degranulation of mast cells in the lungs, and both IL-1β/IL-23 and LPS stimulation also led to an increase in mast cell numbers and degranulation." (PMID 40674143, 2025). "Different cytokine profiles were observed compared to influenza and bacterial pneumonia, with IL-2, IL-1β, IL-8, IL-10, CXCL10, and MCP-1 being highest in the AdV group, while free TGF-β1 was lowest in the AdV group." (PMID 39858309, 2025). "As our data shows that IL-1β production by B cells in influenza infected mice is necessary for optimal establishment of GCs, we wanted to determine if similar mechanisms are at play in human GC B cells." (PMID 40825032, 2025). "In this study, the antibacterial, anti-influenza, and anti-oxidant activities of KZExt, along with its inhibitory effect on IL-1β production in LPS-stimulated cells, were confirmed through in vitro evaluation." (PMID 41010902, 2025). "Using B cell specific ablation of IL-1β production and IL-1β signaling we further confirm that, GC B cells are the primary source of vital IL-1β within the GC and that IL-1β processing by GC B cells post influenza infection is driven by NLRP3 inflammasomes." (PMID 40825032, 2025). "Although key players in the inflammatory response, interleukin-6 (Il6.c) and interleukin-1b (Il1b) also have protective effects after influenza infection and show reduced up-regulation in obese lungs compared to control." (PMID 38728395, 2024). "The secretion of inflammatory cytokines such as TNF-α, IL-1β, and IL-6 post influenza infection also promotes bacterial adhesion and invasion." (PMID 39065060, 2024). "For the target search, we applied a PPI network to identify the top three hub genes associated with influenza (IL-6, HIF1A, and IL-1β)." (PMID 39000173, 2024). "It was reported that significantly higher levels of IL-1β and IL-6 were detected in influenza patients with more severe conditions." (PMID 39000173, 2024). "Next, PPI network analysis identified the top three hub genes associated with influenza (IL-6, HIF1A, and IL-1β)." (PMID 39000173, 2024). "In response to influenza viral entry, epithelial cells induce proinflammatory cytokines and chemokines such as IL-1β, IL-6, TNFα, CCL2, CCL3, and CCL5, which recruit macrophages and neutrophils to the site of infection to help control the virus." (PMID 38112660, 2023). "Inflammasome signaling during natural influenza infection results in, among other events, the local production of IL-1β and IL-18, which are essential for optimal adaptive immune responses to influenza virus infection." (PMID 37153548, 2023). "First, we found that CD64+ macrophages were major producers of pro-IL-1β compared to CD64− cells in influenza-infected aged lungs." (PMID 38077031, 2023). "We used an ex vivo coculture of macrophages and CD8+ T cells isolated from mice previously infected with influenza (42dpi) to assess IL-1β release." (PMID 38077031, 2023). "There was widespread expression of IL-1β in lungs from macaques with severe influenza, and much of this expression was in macrophages, whose density was significantly increased with lethal disease relative to uninfected animals." (PMID 35271686, 2022). "Canonical inflammatory cytokines like TNF-α, IL-1β and interferons, are secreted by virus-infected epithelial and stromal cells during various stages of influenza infection." (PMID 36895258, 2022). "In influenza-induced tissue damage, IL-1β and TNF-α are induced to be expressed in type II alveolar epithelial cells and contribute to alveolar regeneration by acting directly on alveolar epithelial cells via surface receptors and NF-κB signaling pathways." (PMID 36052144, 2022).
influenza (continued). "Lung homogenates were evaluated by multiplex ELISA (Quansys) to quantify several cytokines (TNFα, IFNγ, IL-1α, IL-1β and IL-6) and chemokines (MCP-1, MIP-1α and RANTES) implicated in influenza-mediated acute lung injury 33,34." (PMID 35410323, 2022). "In fact, IL-1β secretion in response to influenza stimulation at 24 h post-vaccination was higher in older adults." (PMID 35822051, 2021). "Previous studies have shown influenza infection can cause the production of TNF-α, IL-1β, IFN-γ, and IL-6." (PMID 34552653, 2021). "SARS-CoV-2-induced IL-1β response was significantly reduced after the influenza vaccination, while poly(I:C) resulted in higher IL-1β production." (PMID 34695164, 2021). "The results showed that influenza infection induced significantly higher mRNA expressions of IL-1β, IL-6, TNF-α, IL-10, MCP-1, IP-10, IFN-γ, and IFN-β in lung compared with non-infection mice." (PMID 35154087, 2021). "The anti-inflammatory activities of sesamin have been shown also, in influenza H1N1-induced peripheral blood mononuclear cells of humans by either the reduction in the expression levels of both IL1B and TNFA genes or the increase in the expression of IL2 gene." (PMID 33578642, 2021). "There was a significant increase in IL-1β and IL-6 mRNA as well as IL-1β and IL-6 cytokine production in aged lung in response to secondary post-influenza infection with S. pneumoniae." (PMID 32545261, 2020). "The NLRP3 inflammasome and its product interleukin-1β (IL-1β) are pivotal mediators of cellular immune responses to influenza, yet, overactivation of these systems leads to side effects, which hamper clinical applications." (PMID 32714571, 2020). "Many influenza-induced cytokines, such as IL-1β and TNF-α, act both as potent activators of NF-κB and are themselves NF-κB target genes, indicating the potential for uncontrolled feed-forward inflammatory activation." (PMID 33239293, 2020). "At an early phase of influenza infection, that is, day 3 there were significantly lower amounts of IL-1β protein in the airways, but substantially higher amounts of type I IFN-β following MitoTEMPO treatment." (PMID 31190565, 2020). "Our findings in ANP32B+/+ and ANP32B−/− mice on the other hand suggest that ANP32B is required for the induction of a subset of pro-inflammatory cytokine responses (TNF-α, MCP-1, IL-1β, and IL-6), upon influenza infection in the murine lung." (PMID 32231671, 2020). "Especially, elderly mice infected with influenza produce less amounts of active IL‐1β even though they have normal levels of pro‐IL‐1β." (PMID 32428336, 2020). "The resultant production of IL‐1β stimulates acute inflammatory responses that play critical roles in defending against influenza infections." (PMID 32428336, 2020). "In summary, our data show that testosterone treatment of females significantly improves influenza disease outcome by dampening IL-1β responses and reducing virus induced lung damage." (PMID 32431696, 2020). "Elderly mice infected with influenza produce less amounts of active IL‐1β due to reductions in the levels of inflammasome‐related proteins, although they produce normal levels of pro‐IL‐1β." (PMID 32428336, 2020). "Released IL‐1β stimulates acute inflammatory responses involved in defense against microbial infections, including influenza." (PMID 32428336, 2020). "In sum, our results demonstrate that there is augmented IL-1β and IL-6 production in aged lung in response to a post-influenza infection with S. pneumoniae." (PMID 32545261, 2020). "In other respiratory viral infections such as influenza, high levels of IL-1β have been detected in bronchoalveolar fluid and plasma from patients with lung injury." (PMID 32655582, 2020). "Collectively, these data suggest that influenza infection drives the expression of IL-1β/inflammasome components (signal 1) in alveolar macrophages, but the inflammasome is not activated nor IL-1β released (signal 2) in the absence of neutrophils." (PMID 29079611, 2018).
influenza (continued). "In line with this view, hippocampal elevations of IL-1β in a mouse model of influenza were limited in mice that had been housed in an EE, whereas IL-6 increases in influenza-exposed mice were not influenced by enrichment." (PMID 30065637, 2018). "To identify the principle population responsible for IL-1β in our influenza model, we isolated these populations by fluorescence-activated cell sorting." (PMID 29079611, 2018). "Examination of IL-1β stained tissue sections from influenza-infected animals further supported the assertion, with IL-1β staining solely restricted to macrophages of influenza-infected mice." (PMID 29079611, 2018). "Accordingly, the markedly reduced levels of cleaved caspase-1 in the lungs of influenza-infected mice after neutrophil depletion is indicative of the absence of the second signal driving inflammasome activation and IL-1β release." (PMID 29079611, 2018). "Second, however, we also demonstrate that levels of IL-1β protein in lung tissue of influenza infected mice were unperturbed by neutrophil depletion—levels of the cytokine would be reduced if neutrophils were a prominent source." (PMID 29079611, 2018). "In lung homogenates, influenza by itself caused mildly elevated levels of TNF-α, IL-1β, IL-6, and IL-10 at 4 days post-infection and to a lesser extent at 10 days after infection." (PMID 29978355, 2018). "We found an increase in the levels of the inflammatory cytokines IL-1α, IL-1β, TNFα, IL-6, IL-12p40, IL-17, and IFNγ, and increased levels of the Type 2 cytokines IL-4 and IL-5, in influenza-infected Stat2−/− mice when compared to WT mice." (PMID 30337919, 2018). "Alveolar macrophages were shown to be the prominent source of IL-1β during influenza infection, and virus triggered the expression of Nod-like receptor protein 3 (NLRP3) inflammasome and pro-IL-1β in these cells." (PMID 29079611, 2018). "Strikingly, BALF IL-1β levels in influenza-infected mice at 24 hours post infection were reduced to control levels following neutrophil depletion." (PMID 29079611, 2018). "In this paper, we demonstrate that IL-1β release during influenza infection is critically dependent on neutrophil-driven activation of the NLRP3 inflammasome in alveolar macrophages and is mediated through the neutrophil antimicrobial peptide mCRAMP." (PMID 29079611, 2018). "Influenza infection induced a variety of inflammatory cytokines such as IL-1β, IL-6, TNFα, IL-8, CCL2, CCL5, and CXCL10 from epithelial and immune cells." (PMID 30337919, 2018). "Given that comparable numbers of alveolar macrophages and neutrophils are observed in the airways at 24 hours post influenza infection in our model, it is extremely likely that alveolar macrophages are the prominent source of IL-1β." (PMID 29079611, 2018). "Lung tissue IL-1β protein and mRNA levels were increased comparably in influenza-infected control and neutrophil-depleted mice." (PMID 29079611, 2018). "These molecules, along with TNF and IL1b (also over-expressed at day 5), are the major cytokines limiting viral replication during influenza infection, recruiting immune cells to the sites of infection and producing inflammation." (PMID 29038764, 2017). "Influenza induces expression of cytokines, i.e., TNFα, IL-1β and IFN-β and chemokines such as KC (murine IL-8) that is inhibited by Eritoran therapy." (PMID 28106157, 2017). "L. paracasei consumption seems to allow an early activation of pro-inflammatory cytokines (IL-1α, IL-1β) and a massive recruitment of immune cells in the lungs after L. paracasei gavage and prior to influenza infection." (PMID 28931041, 2017). "Before influenza infection (day 0, D0), we observed significantly higher levels of pro-inflammatory cytokines IL-1α and IL-1β in L. paracasei-fed mice compared to PBS-fed mice." (PMID 28931041, 2017).